STAT5B (signal transducer and activator of transcription 5B)
Diseases named in the same sentence as STAT5B in open-access papers (continued):
Sharing a sentence is not in itself a finding about the gene and the disease.
T-cell leukemia (15 papers, 2015 to 2025). A malignant disease of the T-lymphocytes in the bone marrow, thymus, and/or blood. "Here, the function of two STAT5B mutations from human T-cell leukemias: one substituting tyrosine 665 with phenylalanine (STAT5BY665F) and the other with histidine (STAT5BY665H), was interrogated." (PMID 40228864, 2025). "The SH2 domain is vital for STAT5B activation, and this study focuses on the impact of two specific missense mutations identified in T cell leukemias, the substitution of tyrosine 665 with either phenylalanine (Y665F) or histidine (Y665H)." (PMID 40163145, 2025). "The insertion of human mutations into the mouse genome permitted a robust comparative investigation and uncovered unexpectedly intricate properties of two human STAT5B variants that had previously been identified in T cell leukemias." (PMID 38903072, 2024). "Here, function of two STAT5B mutations from human T cell leukemias: one substituting tyrosine 665 with phenylalanine (STAT5BY665F), the other with histidine (STAT5BY665H) was interrogated." (PMID 39803507, 2024). "Inactivating mutations in STAT5B, associated with Laron syndrome, have been documented in humans, while potential activating mutations have been observed in patients with T cell leukemias." (PMID 38903072, 2024). "Whole genome sequencing analysis showed that the STAT5B N642H mutation was associated with aggressive mature T-cell leukemia, and RNA-sequencing analysis found that the recurrent STAT5B N642H mutation was present in myeloid neoplasms with eosinophilia." (PMID 36232600, 2022). "This appears paradoxical given prior reports of oncogenic STAT5B mutations, such as STAT5BN642H, which drive proliferation in T-cell leukemias and certain myeloid neoplasms." (PMID 41301421, 2025). "The primary objective of this study was to understand the structural, genomic and pathophysiological impacts of two human leukemic STAT5B mutations, STAT5BY665F and STAT5BY665H, identified in patients with T cell leukemias." (PMID 39803507, 2024). "Tyrosine 665 is the second most abundant mutational target in the STAT5B SH2 domain, with 12 T cell leukemia cases reported in the COSMIC database and 15 cases in the database of the Munich Leukemia Laboratory (MLL)." (PMID 39803507, 2024). "STAT5B and SUZ12 at this level hold diagnostic value for T cell leukemias, while the remaining are relevant to other hematologic malignancies." (PMID 34299796, 2021). "Interestingly, activating mutations have been detected in the IL7-receptor gene IL7R, the mediating kinase JAK3, and its target protein STAT5B in T-cell leukemia." (PMID 28977998, 2017). "STAT5B N642H has further been identified in multiple subtypes of PTCL: 2% of cases of T-LGL, 7/21 (33%) of cases of HSTL, and in T-PLL where it has demonstrated increased colony forming capacity in Jurkat cells, a T-cell leukemia cell line." (PMID 26536348, 2015).
diabetes (12 papers, 2013 to 2026). "Genetic screening identified, in 2 patients with diabetes onset before 1 year of age, 2 likely pathogenic novel variants affecting canonical splicing sites: c.286-12_290del in STAT5B and c.-22-2delA in FOXP3." (PMID 39870583, 2025). "Despite being poorly documented in humans, a correlation of STAT5B deficiency with pathogenesis of diabetes in animal models is well established, supporting the possibility that the variant is responsible for the T1D in the patient." (PMID 39870583, 2025). "For example: IGF1, IGF2 and LEPR, which have previously been associated with diabetes, while STAT5B and ROCK1 have shown weaker associations to the disease." (PMID 32735660, 2020). "Overall, high fat diets, obesity, metabolic syndrome, and diabetes were consistently associated with feminization of liver STAT5b function." (PMID 26959237, 2016). "To correct this defect, we generated transgenic NOD mice expressing constitutively active Stat5b (NOD.Stat5b-CA) in DCs, which conferred protection from diabetes that was associated with an expanded Treg population and a marked reduction in CD8+ T cell frequencies in secondary lymphoid organs." (PMID 41596443, 2026). "Indeed, it has been reported that a diabetes associated genetic interval on chromosome 11 and other genetic intervals may be associated with the increased baseline Stat5b phosphorylation in NOD mice." (PMID 23457589, 2013). "Our data also highlight the important role that tolerogenic Stat5b-expressing DCs play in the reduction of cTregs and induction of eTregs subsets and protection from diabetes in NOD.Stat5b-CA mice." (PMID 41596443, 2026). "We have reported that immunogenic DCs of NOD mice engineered to express active Stat5b are tolerogenic and are successful in treating ongoing diabetes in the preclinical NOD mouse model." (PMID 40247205, 2025). "We found that Stat5b-CA.DCs exhibited the characteristics of tolerogenic DCs and these mice were fully protected against diabetes." (PMID 40247205, 2025). "In agreement with this suggestion, our data showed that transfer of NOD.Stat5b-CA DCs that contain more cDC2 subsets protect NOD mice from diabetes, whereas transfer of DCs of NOD mice that contain more cDC1 do not protect NOD mice from diabetes." (PMID 40247205, 2025). "As we previously reported, NOD mice transduced with the vehicle-treated DCs of NOD.Stat5b-CA mice were fully protected from diabetes." (PMID 40247205, 2025). "Splenic DCs were purified from diabetes-prone NOD mice and diabetes-resistant NOD.Stat5b-CA transgenic mice and their tolerogenic and immunogenic phenotypes were analyzed by FACS." (PMID 40247205, 2025). "Key examples include IRF1, GATA6, SPI1, EPAS1, NFKB2, and STAT5B, which are involved in immune response, cell differentiation, and metabolic regulation, all of which are critical in diabetes pathogenesis." (PMID 39877357, 2024). "Results showed that 7 of the 7 (100%) NOD recipient mice that had been injected with Stat5b-CA.BMDCs were protected against diabetes development." (PMID 32899608, 2020). "Of significance, a single injection of Stat5b-CA.BMDCs into 7- to 8-week-old NOD mice protected the animal from type 1 diabetes, whereas the transfer of Stat5b-CA.BMDCs in which Ezh2 was inhibited have a reduced ability to protect against diabetes." (PMID 32899608, 2020). "Results showed that NOD mice transferred with BMDCs of NOD mice became diabetic within 12 weeks after transfer, whereas the transfer of Stat5b-CA.BMDCs protected NOD mice from diabetes." (PMID 32899608, 2020). "In models of diabetes and obesity, where circulating glucose levels are elevated, we consistently observed feminization of liver STAT5b function, and feminization was at least partially reversed by leptin or resveratrol treatment." (PMID 26959237, 2016).
diabetes (continued). "Investigating these mechanisms, potentially through approaches involving perforin inhibitors or Fas-deficient models, would provide critical insights into the molecular processes by which Tregs mediate the reduction of CD8+ T cells in diabetes-resistant NOD.Stat5b-CA mice." (PMID 41596443, 2026). "Moreover, blockage of USP7 in tolerogenic Stat5b-CA.DCs abrogated their capacity to protect NOD mice from developing diabetes." (PMID 40247205, 2025). "Importantly, the capacity of Stat5b-CA.DCs to protect NOD mice from diabetes were lost when treated with USP7 inhibitor." (PMID 40247205, 2025). "Importantly, inhibition of Ezh2 in tolerogenic Stat5b-CA.BMDCs reduced their ability to prevent diabetes development in NOD recipient mice." (PMID 32899608, 2020). "Furthermore, data reported here showed that the expression of Stat5b-CA of diabetes-resistant C57BL/6 mice restored strong Stat5b DNA-binding activity in the BMDCs of NOD mice." (PMID 32899608, 2020). "We have reported that NOD.CD11cStat5b-CA transgenic mice expressing a constitutively active (CA) form of Stat5b under the control of a CD11c promoter are protected from diabetes and that Stat5b-CA-expressing DCs are tolerogenic and halt ongoing diabetes in NOD mice." (PMID 32899608, 2020). "To validate the capacity of tolerogenic Stat5b-CA.BMDCs to induce antigen-specific immune tolerance in vivo, we investigated their ability to induce immune tolerance in an autoimmune disease setting such as halting ongoing autoimmune diabetes in diabetes-prone NOD mice." (PMID 32899608, 2020). "We also found that following the USP7 blockade, DCs of NOD.Stat5b-CA mice lost their ability to protect NOD mice from diabetes, indicating the important immunoregulatory role of USP7 in the process of autoimmune tolerance mediated by tolerogenic Stat5b-CA.DCs." (PMID 40247205, 2025). "Injection of Stat5b-CA.BMDCs into prediabetic NOD mice halted progression of islet inflammation and protected against diabetes." (PMID 32899608, 2020). "To overcome the Stat5 defect in DCs of diabetes-prone NOD mice, we generated transgenic mice (NOD.CD11cStat5b-CA) expressing a DC-specific, constitutively active form of the Stat5b gene." (PMID 32899608, 2020). "Additional genes include members of the JAK/STAT signaling pathway, e.g. STAT5B or ROCK1, where it has been argued that this pathway is dysregulated in metabolic diseases including obesity and diabetes." (PMID 32735660, 2020). "Of significance, injection of Stat5b-CA.BMDCs into diabetes-prone NOD mice halted ongoing diabetes, in marked contrast to reduced diabetes protection in NOD mice injected with Stat5b-CA.BMDCs in which Ez2 was inhibited." (PMID 32899608, 2020). "STAT5B and ROCK1 are members of the JAk/STAT pathway, which has recently been shown to influence processes relevant for obesity and diabetes." (PMID 32735660, 2020). "To overcome the abnormalities of DCs that are the major contributors to the development of autoimmune responses leading to diabetes in NOD mice, we engineered a transgenic mouse model called NOD.Stat5b-CA mice in which DCs express an active form of Stat5b transcription factor (Stat5b-CA.DCs)." (PMID 40247205, 2025). "Of importance, when treated with USP7 inhibitor, DCs of NOD.Stat5b-CA mice failed to protect NOD recipient mice from developing diabetes." (PMID 40247205, 2025). "We have previously shown that DCs of non-obese diabetic (NOD) mice expressing active Stat5b (Stat5b-CA.DCs) acquire toDCs signature and protect against diabetes." (PMID 40247205, 2025). "Moreover, USP7 inhibition increased Stat5b-CA.DC capacity to promote Th17 cells, restrained Th2 and Treg cells in vivo and, therefore, lost their capacity to protect NOD mice from diabetes." (PMID 40247205, 2025). "Interestingly, the transfer of Stat5b-CA.BMDCs that had also been pretreated with Ezh2 GSK343 inhibitor to NOD mice restored and accelerated diabetes transfer in 50% of the recipient NOD mice." (PMID 32899608, 2020).
eosinophilia (11 papers, 2018 to 2025). "Some activating STAT5B mutations, particularly the N642H mutation, have recently been identified as recurrent in myeloid neoplasms with eosinophilia." (PMID 38254826, 2024). "On the other hand, STAT5B mutations have also been described in T-cell lymphomas with eosinophilia, and it was demonstrated by FACS that the mutation is in the T-cell population and not in eosinophils." (PMID 38254826, 2024). "In 2018, STAT5B N642H was identified as an additional hotspot mutation in the setting of eosinophilia." (PMID 34298741, 2021). "Our findings are the first to identify STAT5B N642H as a recurrent mutation in myeloid neoplasms with eosinophilia." (PMID 30573779, 2019). "We identified STAT5B N642H, an established oncogenic mutation, in 27/1715 (1.6%) cases referred for investigation of eosinophilia." (PMID 30573779, 2019). "The finding of STAT5B N642H as a recurrent mutation in myeloid neoplasia with eosinophilia provides a new diagnostic and prognostic marker as well as a potential target for therapy." (PMID 30573779, 2019). "So, STAT5B-mutated eosinophilia/HES should be reclassified as myeloid neoplasm or CEL." (PMID 38254826, 2024). "The detection of clonality in eosinophilia, such as STAT5B mutations or tyrosine kinase fusion genes, could enable the use of targeted therapies, leading to an improvement in the quality of life and survival of patients." (PMID 38254826, 2024). "The top proteins with the largest log2 fold change in this group included IL-19, STAT5B, CCL17, S100A12, and CCL22—inflammatory mediators known to be associated with AD inflammation and eosinophilia." (PMID 41357518, 2025). "Among the clonality markers described in myeloid hematologic neoplasms or stem cell disorders that are associated with eosinophilia are tyrosine kinase gene rearrangements and JAK1, JAK2, and STAT5B mutations." (PMID 38254826, 2024). "First, in most of our cases eosinophilia was apparent at diagnosis and the level of STAT5B N642H as assessed by Sanger sequencing indicated that the mutation was present in the majority of cells." (PMID 30573779, 2019). "Of the 27 mutated cases, a working diagnosis of hypereosinophilic syndrome (HES; n = 7) or a myeloid neoplasm with eosinophilia (n = 20) had been made prior to the detection of STAT5B N642H." (PMID 30573779, 2019). "Since in elderly persons, many of these mutations with the exception of STAT5B can occur as CHIP mutations, it is recommended to eliminate all possible reasons of reactive eosinophilia before making a CEL, NOS diagnosis based on these alterations in an older person." (PMID 34298741, 2021). "Overall, therefore, we found that 27/1715 (1.6%) eosinophilia patients harboured STAT5B N642H." (PMID 30573779, 2019). "Our findings, however, suggest that STAT5B N642H may be a driver of eosinophilia." (PMID 30573779, 2019). "Somatic gain-of-function (GOF) variants in STAT5B drive leukemias and lymphomas, and variants in the Src homology 2 (SH2) domain were reported in three patients with nonclonal eosinophilia, atopic dermatitis, diarrhea, and urticaria." (PMID 40874233, 2025). "The apparent absence of myeloid neoplasia with eosinophilia in this mouse model may be the result of a number of factors, including the precise expression of STAT5B, the effect of other somatic mutations, the cell type in which STAT5B N642H arises and the rapid onset of T-cell neoplasia." (PMID 30573779, 2019). "Although we cannot exclude the possibility that some T-cell subsets might be part of the mutant clone, our data strongly suggest that STAT5B N642H drives primary eosinophilia irrespective of the presence or absence of additional mutations." (PMID 30573779, 2019). "To test if these mutations might also be associated with persistent eosinophilia, we sequenced known mutation hotspot regions of STAT3 and STAT5B in 153 cases but no variants were seen apart from STAT5B N642H." (PMID 30573779, 2019).
prostate carcinoma (11 papers, 2007 to 2024). A carcinoma that arises from epithelial cells of the prostate gland. "Along with being critical for the survival of prostate cancer cells, high levels of active STAT5b are also linked to early recurrence of the disease." (PMID 36755813, 2022). "STAT5b, on the other hand, is directly linked to the development and growth of prostate cancer." (PMID 36755813, 2022). "eQTL analysis and mRNA quantification indicate that the prostate cancer associated SNPs of chromosome 17 could enhance the expression of STAT5B gene." (PMID 23668334, 2013). "In addition, STAT5b has been implicated in prostate cancer cell invasion." (PMID 19630967, 2009). "The link between activation of STAT5a and STAT5b to the progression of solid tumors in breast and prostate cancer, respectively, is clear but the mechanism behind the developments of these cancers requires further elucidation." (PMID 36755813, 2022). "For example, JAK2/STAT5B promotes tumor proliferation and metastasis in breast and prostate cancers." (PMID 35244291, 2022). "Our model identified several transcription factors associated with prostate cancer metastasis, such as ETS2, HOXC4, STAT3, STAT5B, SOX4 and ZEB2." (PMID 23782521, 2013). "In prostate cancer, differential STAT5a and STAT5b protein expression can be correlated with metastatic potential." (PMID 19630967, 2009). "Substantial cell death occurs in prostate cancer cells when the activation of STAT5b is inhibited." (PMID 36755813, 2022). "However, Nevalainen and colleagues reported that STAT5B induces stem cell properties in prostate cancer cells in line with the increase in nuclear STAT5A/B observed in these tumors in correlation with bad prognosis." (PMID 31557897, 2019). "STAT5a is expressed in nonmetastatic C1D mouse prostate cancer cells, but not in their metastatic C2H counterparts, whereas STAT5b is expressed in both." (PMID 19630967, 2009). "Additionally, STAT5a is expressed in LNCaP human prostate cancer cells but not the more highly migratory PC-3 prostate cancer cell line, but STAT5b levels are comparable." (PMID 19630967, 2009).
T-cell prolymphocytic leukemia (10 papers, 2015 to 2024). A slow-growing type of leukemia (blood cancer) in which too many lymphocytes are found in the bone marrow and/or blood. "Integrated genomic analysis identified another missense mutation Y665F in STAT5B that induces constitutive phosphorylation of mutant protein in patients with T-cell acute lymphoblastic leukemia and T-cell prolymphocytic leukemia." (PMID 36232600, 2022). "A recent publication using integrated genomic sequencing shows gain-of-function mutations in JAK1, JAK3 and STAT5B in T cell prolymphocytic leukaemia (T-PLL), supporting the importance of JAK kinases for T cell lymphoma growth." (PMID 25820993, 2015). "For example, in addition to the pathognomonic alterations of the TCL1 gene, T-cell prolymphocytic leukemia (T-PLL) frequently displays point mutations of JAK1 (6.3% of cases), JAK3 (36.4%), and STAT5B (18.8%)." (PMID 38638855, 2024). "There have revealed multiple mutation hot-spots within SH2 and C-terminal domains in STAT5B, among which N642H has been discovered in various hematological malignancies of T cell origin including T-cell acute lymphoblastic leukemia(T-ALL), T-cell prolymphocytic leukemia(T-PLL), and MEITL." (PMID 34895266, 2021). "Inactivating STAT5B germline mutations have been associated with GH insensitivity (Laron syndrome) and immune pathology, while activating somatic mutations have been identified in patients with T cell large granular lymphoblastic leukemia (T-LGLL) and T-cell prolymphocytic leukemia (T-PLL)." (PMID 39803507, 2024).
acute lymphoblastic leukemia (9 papers, 2016 to 2025). Leukemia with an acute onset, characterized by the presence of lymphoblasts in the bone marrow and the peripheral blood. "The STAT5B N642H hotspot mutation has been commonly found in pediatric T-cell acute lymphoblastic leukemia (T-ALL) and is associated with poor prognosis and an increased risk of relapse." (PMID 41438753, 2025). "For example, STAT5A, STAT5B, and STAT5A/B deletion mutations were generated in a T lymphoblastoid cell line using the CRISPR-Cas9 system to investigate the role of STAT5 in glucocorticoid (GC) resistant T cell-acute lymphoblastic leukemia." (PMID 36232600, 2022).